ZNF618 (zinc finger protein 618)
Description:
Regulates UHRF2 function as a specific 5-hydroxymethylcytosine (5hmC) reader by regulating its chromatin localization.
Synonyms: KIAA1952; NEDD10; FP13169
Tractability: PROTAC: UniProt records ubiquitination sites on it; ubiquitination databases record sites on it.
Gene: Protein-coding gene on chromosome 9 (113,876,052 to 114,056,593, forward strand). Ensembl gene ENSG00000157657.
Subcellular location: Nucleus; Chromosome
Subcellular location (Human Protein Atlas): Nucleoplasm
Gene Ontology:
Molecular function: chromatin-protein adaptor activity; identical protein binding; protein binding; transcription coregulator binding
Biological process: regulation of transcription by RNA polymerase II; chromatin organization
Cellular component: chromatin; chromosome; nucleus; pericentric heterochromatin
Genetic constraint (gnomAD): Loss-of-function variants: 31 observed, 91.19 expected, observed/expected ratio (o/e) 0.34, 90% interval 0.25 to 0.46. The upper end of that interval is the gene's LOEUF score, 0.46, which puts it in group 2 of 6, group 1 being the genes least tolerant of losing a copy. Missense variants: 993 observed, 1,240.9 expected, observed/expected ratio (o/e) 0.8, 90% interval 0.76 to 0.84. Synonymous variants: 520 observed, 517.14 expected, observed/expected ratio (o/e) 1.01, 90% interval 0.94 to 1.08.
Homologues: Orthologues: chimpanzee ZNF618 (99% identical), macaque ZNF618 (99% identical), pig ZNF618 (99% identical), rabbit ZNF618 (98% identical), guinea pig ZNF618 (98% identical), mouse Zfp618 (96% identical), rat Zfp618 (96% identical), dog ZNF618 (94% identical), tropical clawed frog znf618 (65% identical), zebrafish znf618 (48% identical), Drosophila melanogaster Opbp (11% identical). Paralogues in human: FIZ1 (10% identical), ZBTB44 (9% identical).
Diseases named in the same sentence as ZNF618 in open-access papers:
ZNF618 is named in the same sentence as 8 diseases in open-access papers, as found by Europe PMC text mining. Sharing a sentence is not in itself a finding about the gene and the disease. The quoted sentences say what the papers report.
cleft lip (1 paper, 2017). Congenital defect in the upper lip where the maxillary prominence fails to merge with the merged medial nasal prominences. "Association studies have demonstrated that ZNF618 may be involved in the occurrence of cleft lip, high blood pressure, kidney diseases and, in women, in brachial-ankle pulse wave velocity and arterial stiffness." (PMID 28103792, 2017).
glioma (1 paper, 2020). A benign or malignant brain and spinal cord tumor that arises from glial cells (astrocytes, oligodendrocytes, ependymal cells). "While functional role of ZNF618 in tumorigenesis is unknown, its expression has been found to be upregulated in glioma and some other cancers." (PMID 32785098, 2020).
ZNF618 also shares sentences with these, for which no sentence is quoted: cancer (1 paper); cardiovascular diseases (1); high blood pressure (1); kidney diseases (1); neurodegenerative disease (1); theileriosis (1).